HIF1A (hypoxia inducible factor 1 subunit alpha)
Diseases named in the same sentence as HIF1A in open-access papers (continued):
Sharing a sentence is not in itself a finding about the gene and the disease.
breast cancer (continued). "HIF1A (A) and HIF2A (B) gene expression in a combined meta-analysis of 2999 breast cancer patient patients stratified by molecular subtype." (PMID 30670058, 2019). "Hypoxia and high protein levels of HIF-1α and HIF-2α correlate with poor prognosis in breast cancer patients." (PMID 31821370, 2019). "This induced C/EBPδ can suppress FBXW7 in breast cancer, consequently increasing oncogenic mTOR/AKT/S6K1 signaling as well hypoxia-inducible factor-1α (HIF-1α) required for hypoxia adaptation, thereby promoting tumor metastasis." (PMID 30791487, 2019). "We previously demonstrated that, in chemoresistant colon cancer, breast cancer, and malignant pleural mesothelioma, RAS/ERK1/2 inhibition reduces the phosphorylation and the stability of HIF1α, a transcriptional inducer of Pgp, even in normoxia." (PMID 31117237, 2019). "A hypoxic environment in breast cancer can increase the levels of HIF-1α, VE-cadherin, MMP-9, Cdc42, EGFR, p-Akt, and p-mTOR to promote the development of VM via the HIF-1α/VE-cadherin/MMP-9, MMP-2 signaling pathway." (PMID 31993365, 2019). "In solid tumors, including breast cancer, CD133 is generally induced by low oxygen availability via upregulation HIF-1α, even though only in colon cancer cells a physical interaction of HIF-1α with the CD133 promoter was demonstrated." (PMID 31636668, 2019). "The aim of the current paper was to test if tumor hypoxia and HIF-1α, the most robustly hypoxia-induced HIF, contribute to endocrine treatment resistance in breast cancer patients." (PMID 31821370, 2019). "Other investigators demonstrated that Id-1 induced angiogenesis through HIF-1α-mediated VEGF activation in human endothelial cells, breast cancer, and hepatocellular carcinoma." (PMID 31640815, 2019). "In agreement to our findings, a study on six human breast cancer cell lines found high basal levels of VEGF A and low HIF-1α and HIF-2α induction was correlated with improved survival under hypoxia." (PMID 31330834, 2019). "In the case of MDA-MB-468 breast cancer cells, hypoxia-induced induction of ORAI3 is mediated by HIF1α, placing ORAI3 alongside TRPC1 as a HIF1α-inducible ion channel in this model." (PMID 30754719, 2019). "Correlation of HIF-1α, MDR1, and LAPTM4B expression with clinico-pathological features of Breast cancer." (PMID 30746305, 2019). "Elevated O-GlcNAcylation in breast cancer cells decreases TCA metabolite α-ketoglutarate (α-KG), leading to reduction of hypoxia inducible factor 1 alpha (HIF-1α) hydroxylation and interaction with von Hippel-Lindau protein (pVHL)." (PMID 31272438, 2019). "In a study carried out using MDA-MB-231 breast cancer cells, deferoxamine (DFO) induced HIF-1α through ERK1/2 phosphorylation which promoted tumor migration and metastasis." (PMID 31766246, 2019). "The HIF-1α-inducible expressions of GLUT1, HK2, PDK1, and LDHA were low in NRF2-silenced breast cancer cells and, accordantly, levels of hypoxia-inducible glycolysis metabolites such as G6P, F16P, GAP, and lactate were diminished by NRF2-silencing." (PMID 31078780, 2019). "Binding motifs for the hypoxia response regulators and transcription factors HIF1α and HIF1β were present in the ORAI3 promotor in MCF7 cells indicating an ability for HIF1 factors to bind in breast cancer cells." (PMID 30754719, 2019). "In detail, those highly invasive breast cancer cell lines, such as MDA-MB-231 and SKBR3, presented higher expression levels of HIF-1α, whereas the ER positive MCF-7 and T47D cell lines presented lower expression levels of HIF-1α." (PMID 30940798, 2019). "Importantly, we demonstrated that P-cadherin aberrant expression was significantly associated with the expression of HIF-1α, GLUT1, CAIX, MCT1, and CD147 in human primary invasive breast tumors, which is in line with the glycolytic phenotype of P-cadherin-enriched basal-like breast carcinomas." (PMID 31010154, 2019).
breast cancer (continued). "In concordance, Loxl-2 was shown to be upregulated by HIF-1α in a hypoxic tumor microenvironment in hepatocellular cancer, and to induce EMT in colorectal and breast carcinomas." (PMID 31547460, 2019). "Transfection of breast carcinoma cells with NDRG2 decreases the expression and proangiogenic activity of HIF1A and VEGF." (PMID 30635008, 2019). "Of note, in human breast cancer cells, a rapid estrogen action involving ERα-mediated activation of the c-Src/PI3K/AKT/mTOR pathway was accountable for the up-regulation of HIF-1α protein expression." (PMID 29996493, 2018). "In breast cancer cells, WWOX was also found to modulate the expression of glycolysis pathway genes, through hypoxia-inducible transcription factor 1α (HIF1α) regulation." (PMID 30211123, 2018). "The evidence gathered in this work shows that ALDH1A1 promotes robust angiogenesis in vitro and in vivo in breast cancer cell lines inoculated in mice, by inducing VEGF expression and release, as a consequence of upstream HIF-1α activation." (PMID 30541574, 2018). "From the perspective of the mechanisms, our findings demonstrated that XBP1 and HIF-1α are upstream driver genes of MALAT1 in TNBC cells, while Her-2 is an upstream driver gene of MALAT1 in Her-2 positive breast cancer cells." (PMID 29416769, 2018). "Furthermore, in patients with breast cancer, a limited bioinformatics analysis shows that patient outcome (metastases-free survival) is associated with an inverse pattern of metabolism-related (LDH-A and HIF-1α) and immune-associated (CD3E and CD8A, CD4) gene expression." (PMID 30248111, 2018). "In this regard, positive staining for hydroxylated HIF-1α at both VHL binding sites (Pro402 and Pro564) identifies a subset of breast cancer patients with poorer prognosis." (PMID 29996493, 2018). "HIF-1α gene expression was shown to be upregulated in oral squamous cell carcinoma and MCF-7 breast cancer cells by ROS via induced ERK and P13K/AKT signaling." (PMID 29896451, 2018). "Similarly, estrogen/GPER signaling leads to the induction of Snail expression in a NICD/CSL/MAML-dependent manner, suggesting that GPER may cooperate with HIF-1α to potentiate Notch-dependent expression of Snail in breast cancer cells exposed to both hypoxia and estrogen." (PMID 29996493, 2018). "It was reported that, in breast cancer, nuclear FIH expression shows a significant positive correlation with nuclear HIF1α expression." (PMID 30333145, 2018). "Simvastatin has been shown to markedly inhibit tumor angiogenesis in human colorectal cancer and breast cancer by reducing the levels of VEGF and hypoxia-inducible factor-1α(HIF-1α)." (PMID 30402122, 2018). "Work by Zhang indicates that HIF-1α can stimulate CD47 expression, an important factor for maintaining plasticity of the cells, which also enables breast cancer cells to avoid phagocytosis by macrophages." (PMID 30301213, 2018). "In our study, acute hypoxia (6–12 h) briefly increased HIF-1α expression, while chronic hypoxia (48 h) continuously enhanced HIF-2α expression and induced the resistance of breast cancer cells to Paclitaxel (PTX)." (PMID 30340507, 2018). "Stabilization and accumulation of HIF-1α in cancer cells promote metastasis, and HIF-1α expression correlates inversely with Parkin expression in breast cancer specimens." (PMID 29941042, 2018). "In breast cancer cells, the effect of hypoxia on Notch-mediated EMT is mediated by HIF-1α recruitment at the Snail promoter, which in turn potentiates NICD/CSL/MAML-dependent expression of the Snail gene." (PMID 29996493, 2018). "Based on the analysis of datasets derived from thousands of primary tumors of breast cancer patients, CD47 expression was not only significantly correlated with patient survival but also correlated with the expression of HIF-1α targeting genes." (PMID 30061885, 2018).
breast cancer (continued). "Hypoxic breast cancer cells were treated with specific inhibitors of Akt (LY294002), MAPK (AG126), and STAT3 (PF04965842) followed by MAO-A and HIF-1α activities were measured." (PMID 29695771, 2018). "In fact, HIF-1α can overexpress and secrete lysyl oxidase (LOX), lysyl oxidase-like 2 (LOXL2) and LOXL4 in hypoxic breast cancer cells." (PMID 29099748, 2017). "Herein, we also show that IGF1 activates the HIF-1α-dependent expression of GPER, required for the regulation of VEGF in CAFs and breast cancer cells." (PMID 29212519, 2017). "Being a direct transcriptional target of HIF-1α, HINCUT-1 is overexpressed in colon and breast cancer cells under hypoxia and in primary colorectal tumors." (PMID 28789687, 2017). "In biological assays, we showed that IGF1 requires both HIF-1α and GPER to induce VEGF-mediated endothelial tube formation, as evidenced by HUVECs cultured with conditioned medium obtained from CAFs and breast cancer cells treated with IGF1." (PMID 29212519, 2017). "Since STAT3 has been shown to stabilize HIF-1α upon hypoxia in Caki-1, a human renal carcinoma cell line and MCF-7, an estrogen receptor-positive breast cancer cell line, we asked if STAT3 is activated in our experimental model." (PMID 29036915, 2017). "Altogether, these findings suggest that HIF-1α and its transcriptional targets GPER and VEGF are triggered by IGF1 both in breast tumor microenvironmentally derived CAFs and in luminal breast cancer cells." (PMID 29212519, 2017). "We establish in primary patient-derived breast CAFs, and in luminal breast cancer cells that IGF1 triggers the expression of VEGF and its transcriptional regulators HIF-1α and GPER, through the ERK1/2 and AKT transduction pathways." (PMID 29212519, 2017). "In our experimental setup STK33 interacted with hypoxia-stabilized HIF-1α in HCT-116 colon, MIA PaCa2 and MDA-MB-231 breast cancer cells suggesting a potential role of STK33 in hypoxic tumors." (PMID 29100402, 2017). "In this study we demonstrated that hypoxia resulted in mRNA up-regulation of the hypoxic marker CA933 and an up-regulation in HIF1α protein levels, as well as an increase in intracellular ROS levels in MDA-MB-468 breast cancer cells." (PMID 29123322, 2017). "We found that Parkin binds to HIF-1α and promotes HIF-1α degradation through ubiquitination, which in turn inhibits metastasis of breast cancer cells." (PMID 29180628, 2017). "Silencing HIF-1α blocks the expression of P4HA in vitro, and knockdown of P4HA1 inhibits tumor growth and metastasis in breast cancer in vivo." (PMID 28415787, 2017). "Because of the robust increase in HIF-1α and, to a less extent, VEGF-A expression in OID daughters’ normal mammary tissue and tumors, we investigated the levels of angiogenesis in mammary tumors using CD31 as a marker of endothelial cells." (PMID 27339599, 2016). "In human breast cancer, the proangiogenic factor VEGF-A is expressed almost exclusively in macrophages in hypoxic areas, a process largely dependent on HIF-1α, as suggested by experiments performed with murine macrophages." (PMID 27034586, 2016). "Immunohistochemistry revealed that expression of HIF-1α and ALKBH5 was concordant in all human breast cancer biopsies analyzed." (PMID 27590511, 2016). "Second, we have shown that HIF-1α and HIF-2α protein levels are enriched in basal breast cancers relative to luminal tumors." (PMID 27001172, 2016). "HIF-1α serves as a coactivator of TAZ/TEADs complex for the transcription of target genes (such as CTGF) and TAZ serves as a coactivator of HIF-1α for the transcription of target genes (such as PDK1 and LDHA) in hypoxic human breast cancer cells." (PMID 27412635, 2016). "In a conclusion, EMMPRIN plays important roles in breast cancer stem like cells influenced by fibroblasts and cancer cells, inhibits miR-106a/b expression which down-regulates STAT3 and HIF-1α." (PMID 27325313, 2016).
breast cancer (continued). "Immunohistochemical analysis revealed that HIF-1α and ALKBH5 expression were highly correlated in human breast cancer biopsies, suggesting that the data from in vitro and in vivo analysis of breast cancer cell lines are clinically relevant." (PMID 27590511, 2016). "A human breast cancer cell line, MDA-MB-231, exhibited the same result that the forced expression of LY6E upregulated HIF-1α expression levels." (PMID 27589564, 2016). "Furthermore, a gene signature derived from breast cancer exhibiting different gene expression patterns in CAFs and fibroblasts from non-cancerous tissue, demonstrated a significantly increased signature score in endometrial lesions with high stromal HIF-1α expression (p = 0.001)." (PMID 27634881, 2016). "Thus, HIF-1α and Axl as potential therapeutic targets in African breast cancer might be considered." (PMID 26760782, 2016). "In experimental breast cancer models, resistance or sensitivity to EGFR-targeted therapies was dependent on HIF-1α activity in triple negative cell lines." (PMID 26760782, 2016). "We performed immunohistochemistry on sections from 9 representative breast cancer biopsies to analyze ALKBH5 and HIF-1α expression." (PMID 27590511, 2016). "HIF-1α status was investigated in A-549 lung, DU-145 prostate and MCF-7 breast cancer cell lines exposed to bile acids (CDCA and DCA)." (PMID 27416726, 2016). "Hypoxic conditions also promoted microvesicles biogenesis dependent upon HIF1α and RAB22A protein expression, and these microvesicles significantly enhanced the formation of focal adhesions and invasiveness of naïve breast cancer cells." (PMID 27384557, 2016). "The study for the first time indicated that cancer cells and fibroblasts interaction promotes breast cancer cells showing stem-like cells through up-regulation EMMPRIN, and led to inhibiting miR-106a/b expression which targets both STAT3 and HIF-1α expression." (PMID 27325313, 2016). "To evaluate HIF-1α- and PGC-1α-significance as clinical prognostic factors in breast cancer patients, we followed up all patients' groups and correlated their overall and disease free survival with HIF-1α/ PGC-1α levels." (PMID 27780920, 2016). "Compared to the chemical-induced cancer, tumor formation was also followed in the transgenic PyMT breast cancer model by crossing C57BL/6J conditional Hif-1αLysM−/−, Hif-2αLysM−/−, and Hif-1α/2αLysM−/− mice with mice expressing the PyMT oncoprotein." (PMID 27015123, 2016). "We correlated the overexpression of HIF-1α and PGC-1α with patients' survival in an unselected population of breast cancer patients." (PMID 27780920, 2016). "Our results demonstrate a novel modulation of HIF-2α in breast cancer cells, explaining the opposing regulation between HIF-1α and HIF-2α in hormone-responsive breast cancer." (PMID 27105516, 2016). "The role of HIF-1α in the later stages of metastasis, such as bone colonization by breast cancer cells, has been tested in mouse models using MDA-MB-231 cells expressing a constitutively active or dominant negative form of HIF-1α." (PMID 27706047, 2016). "In mouse mammary carcinoma (BA) xenografts, porfimer-PDT led to an increase in HIF-1α, BIRC5, and VEGF protein levels." (PMID 26657503, 2016). "Taken together with our previous study, we have now identified four discrete mechanisms of crosstalk between HIF-1α and TAZ that serve to increase the activity of both pathways and drive breast cancer progression." (PMID 26059435, 2015). "Our study reports herein that not only tamoxifen-resistant breast cancer cells display altered glycolysis compared to tamoxifen-sensitive cells but also Akt/mTOR and AMPK signaling molecules are attributed to HIF-1α-regulated glucose metabolism in these cells." (PMID 26158266, 2015). "To validate our results in human tumours, we first performed an immunohistochemical analysis on human breast cancers using anti-UCHL1 and anti-HIF-1α antibodies." (PMID 25615526, 2015).
breast cancer (continued). "In a second approach to verify the IHC with the HIF-1α and HIF-2α antibodies we cultured MCF-7 breast cancer cells under control (21% oxygen) and hypoxic (1% oxygen) conditions for 72 h." (PMID 25955753, 2015). "Hypoxia increased the expressionof HIF-1α and HIF-2α in MCF-7 breast cancer cells, whereas treatment with R. algida extract (225 and 360 μg/mL) possibly decreased HIF-1α and HIF-2α protein expression in cells exposed to hypoxia for 48 h." (PMID 26279639, 2015). "TAZ was reported to interact with HIF-1α and positively regulate HIF-1 transcriptional activity in a breast cancer cell line that was selected for metastasis to bone." (PMID 26059435, 2015). "The ectopic expression of miR-33b downregulated the expression of ADAM9, HMGA2, LDHA, SALL4, SNAI2 and Twist1 by more than 30% but had minimal effects on HIF-1α, RAC1, Yes1 and ZEB1 in these two breast cancer cell lines." (PMID 25919570, 2015). "In our in vitro model, we demonstrated that hypoxia-induced by CoCl2 showed increased HIF1-α accumulation and HIF activation in MCF-7 breast cancer cells, which in turn promoted the EMT." (PMID 26174737, 2015). "OA, a natural product from Scutellaria, can upregulate SIRT3 expression and inhibit glycolysis in breast cancer cells under hypoxia through enhancing SIRT3-mediated stabilization and activation of HIF1α." (PMID 25855962, 2015). "More recently, we showed that MCF-10A cells overexpressing ERBB2 and ERBB2-positive breast cancer cells stabilizes HIF-1α levels and that HIF-1α is required for ERBB2 oncogenesis in vivo and anoikis resistance in vitro." (PMID 25596742, 2015). "PCRanalysis of subgroup of breast cancers, 84.2% expressed HIF-1α protein and its transcripts, while only 66.7% expressed VEGF transcripts simultaneously with the HIF-1α protein and its transcripts." (PMID 26046764, 2015). "For example, it was shown that in breast cancer cell lines the modulation of bioenergetic functions is due to the capacity of DHA to activate the AMPK signalling and negatively regulate the HIF-1α functions." (PMID 26339588, 2015). "Comparison of HIF-1α, PKM2 and ISCU1/2 protein expression in metastatic breast cancer cells and metastatic melanoma cells in the presence and absence of methyl sulfone and hypoxia reveals relatively similar patterns of expression." (PMID 26536104, 2015). "Given the relevance of the interplay between inflammation and hypoxia in tumor progression, in this study we decided to investigate the role of HIF-1α and NFκB in MDAMB231 breast cancer cell migration under hypoxic conditions and in the presence of IL-1β." (PMID 26696754, 2015). "We generated MCF-7 breast cancer cells stably expressing HIF-1α (MCF-7/HIF-1α), which were resistant to endocrine therapy and found that targeting HIF-1α reversed endocrine resistance both in vitro and in vivo." (PMID 25929338, 2015). "The MDA-MB-231 human breast cancer cell line is an invasive and metastatic TNBC cell line that strongly expresses both HIF-1α and HIF-2α proteins under hypoxia." (PMID 26305551, 2015). "Next, we have found that HIF-1α and GPER are required for endothelial tube formation and cell migration stimulated by VEGF as well as for copper-induced proliferation of breast cancer cells." (PMID 26415222, 2015). "Pretreatment with R. algida significantly suppressed the hypoxia-induced proliferation and expression of HIF-1α and HIF-2α in MCF-7 breast cancer cells." (PMID 26279639, 2015). "This is apparently the opposite of the observation from breast cancers, where DEC2 promoted VHL-independent degradation of HIF-1α." (PMID 25884381, 2015). "Previous finding reported significant inhibitions of tumor growth and tumor angiogenesis through EGCG; in addition to that, a major green tea catechin inhibited the activation of HIF-1α and NF-κB and decreased VEGF expression in breast carcinoma cells." (PMID 25977926, 2015).